CHEK2 (checkpoint kinase 2)
Diseases named in the same sentence as CHEK2 in open-access papers (continued):
Sharing a sentence is not in itself a finding about the gene and the disease.
breast cancer (continued). "The risk of breast cancer at age 70 years in CHEK2*1100delC heterozygotes is almost as high as that for BRCA1 and BRCA2 mutation heterozygotes." (PMID 29682443, 2018). "A more intermediate risk of developing breast cancer is conferred by germline mutations in the genes CHEK2, ATM, PALB2, and NBS1, which are, in the general population, more prevalent than mutations in the high risk breast cancer genes." (PMID 30116257, 2018). "The lifetime risk of developing breast cancer among women with a CHEK2 mutation has been reported to be approximately 25%." (PMID 30256826, 2018). "Results from logistic regression analysis confirmed the association of PALB2 mutations with family history of PC (P = .029) or breast cancer (P = .0056) and the association of CHEK2 mutations with family history of colorectal cancer (P = .014)." (PMID 31497750, 2018). "The patient's 61 year old sister was diagnosed with breast cancer at 51 years of age, she had previous multi‐gene panel testing performed, which showed the c.1283C>T pathogenic AJ founder mutation in the CHEK2 gene." (PMID 30152102, 2018). "Here we note that ATM and CHEK2 have recently been added to NCCN’s list of genes with associated medical action for breast cancer." (PMID 29945567, 2018). "Mutations of CHEK2 are also associated with increased risk of kidney, thyroid, prostate, and breast cancers." (PMID 30046434, 2018). "In all patients with CHEK2 mutation, second neoplasms developed many years after the first diagnosis: breast cancer 15 years post-nephrectomy; renal cancer 2 years post-nephrectomy; and meningioma 9 years post-nephrectomy." (PMID 29682443, 2018). "Current research has shown discrepancies in the level of breast cancer risk in families with CHEK2 mutations suggesting that there are additional factors that influence the risk of breast cancer in these families in addition to the CHEK2 mutation." (PMID 29659587, 2018). "CHEK2 missense variant I157T is found to be associated with a 1.5-fold risk of breast cancer, and CHEK2*1100delC heterozygosity is associated with a three-fold risk of breast cancer in women in the general population." (PMID 29682443, 2018). "The novel c.1232G>A is a truncating and function disrupting mutation of the CHEK2 gene, identified in an early onset breast cancer proband." (PMID 29271107, 2018). "In this population, however, new mutations of CHEK2 gene, which moderately increases risk of breast cancer in heterozygotes, were found in rare patients from a few tested ethnic groups." (PMID 29157216, 2017). "We examined the presence of four mutations in CHEK2 gene in 100 breast cancer patients with a personal and/or family history of breast cancer." (PMID 28680382, 2017). "CHEK2 truncating mutations, and c.1100delC alone were also associated with increased risks of breast cancer; however below an OR of 2, thus classifying CHEK2 as a low risk gene for FBC." (PMID 28649662, 2017). "Two of the women had a positive family history of breast cancer and five women had a CHEK2 mutation (one case had both)." (PMID 28265306, 2017). "We detected pathogenic mutations in nine of the 99 women in this group involving the ATM, BRCA1, CDH1, and CHEK2 genes, all of which have been associated with an increased risk of bilateral breast cancer in the previous studies." (PMID 28281021, 2017). "Women with a truncating CHEK2 mutation have a breast cancer risk that is about three fold higher than average and women with both a family history and a CHEK2 mutation have a five-fold increased risk." (PMID 28265306, 2017). "There are only few studies in some countries investigating the possible relationship between IVS2 + 1G > A CHEK2 gene mutation and an increased risk of breast cancer." (PMID 28680382, 2017). "Female CHEK2 and NBN mutation carriers are at an increased lifetime risk of developing breast cancer (2-fold for CHEK2 and 3-fold for NBN carriers)." (PMID 28591191, 2017).
breast cancer (continued). "Another variant, the missense I157T (c.470T>C) in the FHA domain of CHEK2, is associated with a milder elevation in the risk and was observed in 7.4% of unselected female breast cancer patients, in 5.5% of familial patients, and in 5.3% of population controls." (PMID 28874143, 2017). "There were a disproportionately large number of CHEK2 c.1100delC mutations which have been postulated to be enriched in bilateral breast cancer cases." (PMID 28281021, 2017). "Mutations in the PTEN gene have also been linked to both male and female breast cancer, as additionally have mutations in CHEK2." (PMID 27286002, 2017). "A positive case of CHEK2 mutation IVS2 + 1G > A was associated with hereditary breast cancer and the other found to have a sporadic nature." (PMID 28680382, 2017). "Mutations in cell-cycle checkpoint kinase 2 (CHEK2) are associated with an elevated risk for breast cancer." (PMID 28874143, 2017). "Of these women, 458 (15%) had a first-degree relative with breast cancer and 356 (12%) had a CHEK2 mutation (49 truncationg and 307 missense)." (PMID 28265306, 2017). "On the basis of results obtained from different countries with bigger samples, the association between increased risk of breast cancer and CHEK2 gene mutation has been confirmed." (PMID 28680382, 2017). "Contrasting the risk assessments of single amino acid substitutions of the CHEK2, it has been estimated that the 1100delC-variant confers a two-fold elevated risk of both breast cancer and prostate cancer." (PMID 27708748, 2016). "This indicates that SFCM from CHEK2-deficient fibroblast cells can enhance the EMT process in breast cancer cells." (PMID 27484185, 2016). "We also found evidence of association with breast cancer risk for three variants in CHEK2, c.349A>G OR 2.26 (95% CI 1.29 to 3.95), c.1036C>T OR 5.06 (95% CI 1.09 to 23.5) and c.538C>T OR 1.33 (95% CI 1.05 to 1.67) (p≤0.017)." (PMID 27595995, 2016). "Both studies indicated that homozygotes had increased breast cancer risk compared with the heterozygotes of CHEK2*1100delC." (PMID 27900359, 2016). "Two specific disease-related CHEK2 variants, c.1100delC and p.Ile157Thr, were identified at high frequencies of 0.8 and 0.5%, respectively, in women with breast cancer." (PMID 26681312, 2016). "Previously, another CHEK2 mutation, the protein truncating c.1100delC has been associated with poor prognosis of breast cancer patients." (PMID 27716369, 2016). "In particular, CHEK2*1100delC is prevalent in the Caucasian population, and a large cohort study demonstrated that it was a rare disease-causing variant for breast cancer whose odds ratio for unselected patients was 2.7." (PMID 27900359, 2016). "They found the CHEK2*1100delC variant at a frequency of 1.1 % in controls, 5.1 % in cases with a family history, and 13.5 % in cases with a family history of male breast cancer." (PMID 27716388, 2016). "A novel recurrent CHEK2 Y390C mutation has been recently identified in high-risk Chinese breast cancer patients." (PMID 27484185, 2016). "Mutations in CHEK2 have been reported to be possibly associated with breast cancer and liposarcoma development." (PMID 26768750, 2016). "To further study the effect of CHEK2 down-regulation on breast cancer cells, we investigated the paracrine effect of CHEK2 deficient fibroblasts on the mesenchymal and epithelial markers of MDA-MB-231 cells." (PMID 27484185, 2016). "Other mutations in the CHEK2 gene contributing to breast cancer risk are negligible in the Dutch population." (PMID 26553136, 2015).
breast cancer (continued). "The CHEK2 p.I160M missense mutation was detected in a Malay patient who was diagnosed with breast cancer at the age of 43 years old." (PMID 25629968, 2015). "In total, 134 breast cancer cases and 114 controls were successfully screened for the 1100delC variant of the CHEK2 gene using the ASO-PCR technique." (PMID 25674498, 2015). "We screened a cohort of 2334 Chinese women with operable primary breast cancer who received a neoadjuvant chemotherapy regimen for CHEK2 H371Y germline mutations." (PMID 25884806, 2015). "The aim of this study is to identify the CHEK2 gene germline mutations among high-risk breast cancer patients and its contribution to the multiethnic population in Malaysia." (PMID 25629968, 2015). "One recent study suggested that breast cancer patients with CHEK2 1100delC mutation had a worse survival beyond 6 years after diagnosis than did non-carriers." (PMID 25884806, 2015). "Two studies have suggested that the CHEK2 1100delC mutation is associated with poor recurrence-free survival in breast cancer, indicating that patients with CHEK2 1100delC mutation have an aggressive phenotype." (PMID 25884806, 2015). "CHEK2*1100delC is a moderate-risk breast cancer susceptibility allele with a high prevalence in the Netherlands." (PMID 26553136, 2015). "Another missense mutation, CHEK2 p.R180C was detected in a Malay patient who was diagnosed with early onset breast cancer, at the age of 15 years old." (PMID 25629968, 2015). "The most extensively studied CHEK2 protein truncating mutation, c.1100delC was reported to confer a two-fold increased breast cancer risk among Dutch population." (PMID 25629968, 2015). "The CHEK2 p.I160M missense mutation was previously reported in 1/516 (0.2%) German familial breast cancer patients." (PMID 25629968, 2015). "The cell-cycle checkpoint kinase 2 (CHEK2) is an important signal transducer of cellular responses to DNA damage, whose defects has been associated with increased risk for breast cancer." (PMID 25674498, 2015). "The purpose of the study was to determine the frequency of CHEK2 1100delC mutation and the implication of CHEK2 as a breast cancer susceptibility gene in the Moroccan population." (PMID 25674498, 2015). "This study aimed to evaluate the contribution of germline BRCA1, BRCA2 and PALB2 mutations and the CHEK2 c.1100delC allele to breast cancer in a high-risk South African cohort." (PMID 26577449, 2015). "The lifetime risk of breast cancer for a female CHEK2*1100delC mutation carrier from the general population is 20–25 %, increasing to 35–45 % in a familial breast cancer setting." (PMID 26553136, 2015). "The CHEK2 1100delC mutation has been reported to confer a twofold increased risk of breast cancer among carriers." (PMID 25674498, 2015). "Previous studies showed that breast cancer patients with the CHEK2 1100delC mutation had a worse disease-free survival than did patients without this mutation." (PMID 25884806, 2015). "In this case-control study we performed the CHEK2 1100delC mutation analysis by ASO-PCR in 134 breast cancer patients and 114 unaffected control individuals." (PMID 25674498, 2015). "Other than this intragenic deletion, a 23 Kb duplication in a single Italian breast cancer patient is the only other known CHEK2 rearrangement variant." (PMID 26506619, 2015). "CHEK2 encodes the checkpoint kinase 2 protein, and germline CHEK2 mutations have been associated moderately elevated risk for breast cancer, with an odds ratio of 2.7 for unselected breast cancer cases." (PMID 26484312, 2015). "CHEK2 1100delC, a truncating mutation that abrogates the kinase activity of the protein, confers an approximately 2-fold increase in breast cancer risk." (PMID 25884806, 2015). "No previous studies have investigated the association between CHEK2 germline mutation and response to neoadjuvant chemotherapy in breast cancer." (PMID 25884806, 2015).
breast cancer (continued). "The CHEK2 1100delC variant was found in women suffering from breast cancer with familial Li-Fraumeni syndrome." (PMID 25674498, 2015). "Our previous study suggested that the recurrent CHEK2 H371Y mutation is a novel pathogenic mutation that confers an increased risk of breast cancer." (PMID 25884806, 2015). "In our previous study, we identified a novel recurrent CHEK2 H371Y mutation in Chinese women, and this mutation decreases CHEK2 activity and confers an approximately 2.4-fold increase in breast cancer risk." (PMID 25884806, 2015). "CHEK2 has been described as a low-penetrance gene because its inherited mutations appear less severe, leading to an increase in the risk of breast cancer in women and prostate cancer in men." (PMID 24986639, 2014). "In 33 out of 420 (7.9%) women consecutively diagnosed with breast cancer, we detected one of four analyzed CHEK2 mutations: I157T, 1100delC, IVS2 + 1G > A or del5395." (PMID 24713400, 2014). "We identified a new 23-kb duplication in the CHEK2 gene extending from intron 5 to 13 that was associated with breast cancer in the family." (PMID 24986639, 2014). "The germline mutations of CHEK2, especially the truncating ones confer low-penetrance breast cancer predisposition that contribute significantly to familial clustering of breast cancer at the population level." (PMID 24713400, 2014). "In this study, we analyzed the association of CHEK2 mutations with the risk of development of breast cancer in women of North-Central Poland." (PMID 24713400, 2014). "Recent studies have indicated that CHEK2 functions as a moderately effective cancer susceptibility gene; mutations in CHEK2 predispose individuals to breast cancer as well cancer of other sites." (PMID 23806170, 2013). "Carriers of the CHEK2 c.1100delC mutation have an increased risk of bilateral breast cancer and male breast cancer." (PMID 23586058, 2013). "As a result, a known moderate susceptibility indel variant (CHEK2 1100delC) and a catalogue of 11 rare variants presenting signs of association with breast cancer were identified." (PMID 23409019, 2013). "The relevance of CHEK2 mutations as a screening target for an elevated risk of breast cancer is of interest." (PMID 23806170, 2013). "Another CHEK2 variant, CHEK2 p.I157T, which is located in exon 3 of the gene, is associated with lower breast cancer risk (~1.5)." (PMID 23586058, 2013). "Certain mutations in CHEK2 are reproducibly associated with increased risks of female breast cancer." (PMID 23586058, 2013). "The role of CHEK2 mutations in breast cancer predisposition has been investigated previously in several studies conducted in Asia." (PMID 23806170, 2013). "A particular germline mutation, CHEK2 c.1100delC, has been shown to increase breast cancer risk 2-fold." (PMID 23586058, 2013). "The association between the CHEK2 gene and breast cancer risk has been supported mainly by case-control studies of founder mutations such as 1100delC, I157T (frequent in northern and eastern Europe) or the Polish founder mutation IVS2+1 G > A (c.444+1G > A)." (PMID 22114986, 2011). "As part of an international breast cancer genetics study aiming to investigate candidate genes conferring an intermediate-risk of breast cancer, we mutation screened the coding exons and the adjacent proximal introns of CHEK2 in 1415 cases and 1204 controls." (PMID 21569354, 2011). "This demonstrates that, in populations without founder mutations, an aggregate of rare variants makes CHEK2 an appreciable breast cancer risk gene." (PMID 22114986, 2011). "The CHEK2*1100delC deletion, falling in the kinase domain of the protein, has been widely studied for its contribution to inherited breast cancer susceptibility." (PMID 21569354, 2011). "Both protein-truncating variants and some missense substitutions in CHEK2 confer increased risk of breast cancer." (PMID 21244692, 2011).
breast cancer (continued). "Checkpoint kinase 2 (CHEK2) is a moderate penetrance breast cancer risk gene, whose truncating mutation 1100delC increases the risk about twofold." (PMID 21542898, 2011). "That protein-truncating variants in CHEK2 confer a moderately increased risk of breast cancer is well established." (PMID 21244692, 2011). "Though CHEK2 has been identified as an intermediate breast cancer susceptibility gene, only a small proportion of high-risk families have been explained by genetic variants located in its coding region." (PMID 21569354, 2011). "Little similarity was seen between the gene list of 188 CHEK2 1100delC-associated genes and eight gene lists from previously published gene-expression signatures predicting survival or breast cancer subtype." (PMID 21542898, 2011). "Here we used this approach to analyze CHEK2 mutation-screening data from a population-based series of 1,303 female breast cancer patients and 1,109 unaffected female controls." (PMID 21244692, 2011). "This study shows that CHEK2 harbors many rare sequence variants that confer increased risk of breast cancer and that a substantial proportion of these are missense substitutions." (PMID 21244692, 2011). "The OR of CHEK2 mutation carriers was 4.15 (95% CI = 1.38 to 12.50), suggesting that CHEK2 contributes to hereditary risk of breast cancer." (PMID 22114986, 2011). "We further found an association between the CHEK2 1100delC signature of 188 genes and breast cancer relapse." (PMID 21542898, 2011). "Regarding the association of CHEK2 with breast cancer, it is of interest that also one borderline significant SNP is located in a gene breast carcinoma amplified sequence 3 (BCAS3) involved in this pathway." (PMID 20548946, 2010). "The series had been used previously to determine the frequency of mutations in the BRCA1, ATM, NBS1 and CHEK2 genes as well as to characterize more common polymorphisms studied by the Breast Cancer Association Consortium." (PMID 21108795, 2010). "It is also true that if a woman is found to be a CHEK2 carrier and has a family history of breast cancer, she is likely to be at high risk of breast cancer." (PMID 19401704, 2009). "Female carriers of CHEK2 mutations have a moderate two to three fold increased risk to develop breast cancer." (PMID 19607694, 2009). "Germline mutations in CHEK2 are identified in up to 5% of breast cancer families, albeit that their prevalence varies widely among populations." (PMID 19607694, 2009). "One particular CHEK2 germline mutation, c.1100delC, has been shown to be associated with elevated breast cancer risk." (PMID 19338683, 2009). "In other studies, the specific CHEK2 c.1100delC frameshift mutation was shown to be associated with an elevated breast cancer risk and it has been suggested that it contributes to a hereditary breast and colorectal cancer phenotype." (PMID 19338683, 2009). "Additional investigations of CHEK2 and French Canadian breast cancer, utilizing large panels of familial and/or sporadic cases, would be necessary to refute the notion that additional CHEK2 susceptibility alleles exist in the French Canadian population." (PMID 18706089, 2008). "In the current study, 25 French Canadian breast cancer patients and 25 healthy controls were fully screened for variants within the CHEK2 gene." (PMID 18706089, 2008). "Nevertheless, the strength of the model relies in its ability to compute extensive family history, and mutations in other genes relevant to breast cancer, such as CHEK2, to calculate the probability of carrying a mutation in the BRCA genes." (PMID 18627636, 2008). "Germline mutations in both BRCA2 and CHEK2 are associated with an increased risk for male breast cancer." (PMID 18797466, 2008).